PYROXD1 (pyridine nucleotide-disulphide oxidoreductase domain 1)
Description:
Flavoprotein whose role is to protect RTCB, the catalytic subunit of the tRNA ligase complex (tRNA-LC) involved in tRNA splicing and unfolded protein response, from oxidative inactivation. It directly binds and shields the catalytic center of RTCB, prior to guanylylation, when it is inactive and its active site is vulnerable to oxidation under aerobic conditions. The interaction of PYROXD1 with RTCB is allosterically regulated by NAD(P)H binding and reduction of its FAD cofactor, while reoxidation of PYROXD1 thanks to its NADPH dehydrogenase activity triggers the timed release of RTCB, enabling its subsequent activation. Thereby, this protective mechanism may also function as a molecular timer, regulating RTCB activation through controlled release.
Synonyms: DKFZp762G094; FLJ22028; MFM8
Tractability: Small molecule: a structure with a bound ligand is known. PROTAC: ubiquitination databases record sites on it.
Gene: Protein-coding gene on chromosome 12 (21,437,615 to 21,471,250, forward strand). Ensembl gene ENSG00000121350.
Subcellular location: Nucleus; Cytoplasm, cytosol; Cytoplasm, myofibril, sarcomere
Subcellular location (Human Protein Atlas): Nuclear speckles
Gene Ontology:
Molecular function: molecular sensor activity; NAD(P)H oxidase H2O2-forming activity; NADH dehydrogenase activity; NADPH dehydrogenase activity; protein binding; oxidoreductase activity
Biological process: cellular response to oxidative stress; tRNA exon ligation
Cellular component: nucleus; sarcomere; cytoplasm; cytosol
Genetic constraint (gnomAD): Loss-of-function variants: 17 observed, 23.04 expected, observed/expected ratio (o/e) 0.74, 90% interval 0.5 to 1.11. The upper end of that interval is the gene's LOEUF score, 1.11, which puts it in group 4 of 6, group 1 being the genes least tolerant of losing a copy. Missense variants: 223 observed, 268.88 expected, observed/expected ratio (o/e) 0.83, 90% interval 0.74 to 0.93. Synonymous variants: 98 observed, 102.06 expected, observed/expected ratio (o/e) 0.96, 90% interval 0.81 to 1.14.
Gene-disease validity (ClinGen):
ClinGen rates the evidence that PYROXD1 causes each of these diseases.
myofibrillar myopathy 8 (autosomal recessive): Definitive.
Homologues: Orthologues: chimpanzee PYROXD1 (99% identical), macaque PYROXD1 (97% identical), rabbit PYROXD1 (91% identical), guinea pig PYROXD1 (88% identical), dog PYROXD1 (87% identical), pig PYROXD1 (87% identical), rat Pyroxd1 (85% identical), mouse Pyroxd1 (85% identical), tropical clawed frog pyroxd1 (66% identical), zebrafish pyroxd1 (62% identical), Drosophila melanogaster Pyroxd1 (45% identical), Caenorhabditis elegans C26D10.3 (31% identical). Paralogues in human: TXNRD2 (18% identical), TXNRD1 (18% identical), TXNRD3 (18% identical), AIFM1 (15% identical), GSR (15% identical), AIFM3 (15% identical), DLD (15% identical).
Diseases named in the same sentence as PYROXD1 in open-access papers:
PYROXD1 is named in the same sentence as 20 diseases in open-access papers, as found by Europe PMC text mining. Sharing a sentence is not in itself a finding about the gene and the disease. The quoted sentences say what the papers report.
colorectal cancer (3 papers, 2014 to 2022). A primary or metastatic malignant neoplasm that affects the colon or rectum. "For the first time we studied PYROXD1 expression level in colorectal cancer and we showed that PYROXD1 is up regulated in this cancer." (PMID 35845311, 2022). "PYROXD1 sinks Murine was reported to reduce the proliferation ability of colorectal cancer cells and could act as a tumor promoter." (PMID 36334145, 2022).
congenital myopathy (2 papers, 2019 to 2022). "Recessive mutations in PYROXD1, encoding an oxidoreductase, were recently reported in families with congenital myopathy or limb-girdle muscular dystrophy." (PMID 31455395, 2019). "Recently, PYROXD1 mutations were described in patients with slowly progressive congenital myopathy, and analysis of the muscle biopsies revealed multiple internal nuclei and cores, as well as myofibrillar inclusions." (PMID 31455395, 2019). "Studies have shown that PYROXD1 was related to congenital myopathy and regulated the development of muscle tissues." (PMID 36334145, 2022).
limb-girdle muscular dystrophy (2 papers, 2019 to 2020). Limb-girdle muscular dystrophy (LGMD) is a heterogeneous group of muscular dystrophies characterized by proximal weakness affecting the pelvic and shoulder girdles. "The physiological role of PYROXD2, particularly in skeletal muscle, remains largely unclear but recent data show that genetic variants in its family member PYROXD1 induces early‐onset myopathy and limb girdle muscular dystrophy characterized by abnormal myofibrils, nuclei, and mitochondria." (PMID 32892688, 2020). "Additional PYROXD1 cases were reported with childhood or adult-onset limb-girdle muscular dystrophy (LGMD)." (PMID 31455395, 2019).
myofibrillar myopathy (2 papers, 2019). "Overall and in view of the histological characteristics on biopsies as cores, central nuclei, and sarcoplasmic aggregates, PYROXD1-related myopathy can be considered as mixture of core myopathy, centronuclear myopathy, and myofibrillar myopathy." (PMID 31455395, 2019). "Vacuoles, another hallmark of myofibrillar myopathy, have not been detected in any PYROXD1 biopsy." (PMID 31455395, 2019).
Onset (2 papers, 2019 to 2020). The age group in which disease manifestations appear. "Here we describe a consanguineous family of individuals affected with late-onset myopathy and homozygous PYROXD1 missense variants (NM_024854.5:c.464A>G [p.Asn155Ser]) expanding our understanding of the possible disease phenotypes of PYROXD1-associated myopathy." (PMID 32037607, 2020).
breast tumors (1 paper, 2011). "Scatter plots showed that CARS and PYROXD1 were not only highly correlated with cell surface NIS protein level but also differentially regulated between NIS-positive and NIS-negative breast tumors." (PMID 21989294, 2011).
Osteopenia (1 paper, 2026). Osteopenia is a term to define bone density that is not normal but also not as low as osteoporosis. "Biallelic variants in PYROXD1 are associated with a life limiting muscle and connective tissue disorder characterised by generalised muscle weakness, breathing and feeding difficulties, distal laxity, hypernasal speech, blue sclera and osteopenia." (PMID 41772734, 2026).
scoliosis (1 paper, 2022). A congenital or acquired spinal deformity characterized by lateral curvature of the spine. "Scoliosis and flexion contracture of the thumb were also described in the PYROXD1-linked form of MFM." (PMID 36104822, 2022).
myopathy (6 papers, 2019 to 2026). A disease of the muscle in which the muscle fibers do not function properly. "For P2, P3 and P4, the homozygous variant c.464A > G p.Asn155Ser in PYROXD1 (ENST00000240651.9) caught our attention because of its recent association with myopathy." (PMID 30515627, 2019). "In conclusion, our study shows that PYROXD1 should be considered as a causative gene also in later-onset unsolved myopathies, which resemble LGMD." (PMID 30515627, 2019). "We expand the genetic spectrum of PYROXD1-related myopathy and report for the first time a deep intronic mutation." (PMID 31455395, 2019). "Myopathy associated with PYROXD1 pathogenic variants is rare and reported in only 17 individuals." (PMID 32037607, 2020). "We report here new patients with recessive PYROXD1 variants underlying myopathy phenotypes." (PMID 30515627, 2019). "For example, repurposing of therapies targeting excitation–contraction coupling and Ca2+ homeostasis can be envisaged for CACNA1S or the SOCE pathway, or anti-oxidant modulators for PYROXD1-related myopathy." (PMID 38982518, 2024). "Similar to the original report on PYROXD1-related myopathy, rectus femoris was less affected than the vasti muscles." (PMID 30515627, 2019). "We also compared all published and new PYROXD1 patients and provide an overview on the clinical, histological and genetic spectrum of PYROXD1-related myopathy and draw a genotype/phenotype correlation." (PMID 31455395, 2019). "Overall, the clinical, histological, and ultrastructural features of our patients were strongly suggestive of PYROXD1-related myopathy." (PMID 31455395, 2019). "The combination of multiple internal nuclei and cores within single fibers constitutes a typical histopathological indication of PYROXD1-related myopathy." (PMID 31455395, 2019). "Since the clinical and histopathological features of P3 were strongly indicative of PYROXD1-related myopathy, we extracted the skeletal muscle RNA, performed quantitative RT-PCR, and analyzed the reverse transcribed PYROXD1 coding sequence." (PMID 31455395, 2019). "Muscle MRI may help to distinguish PYROXD1 myopathy from other myopathies, as our patients showed an unusual preference for anterolateral thigh muscles." (PMID 30515627, 2019). "Regular monitoring of pulmonary function is therefore mandated in PYROXD1 myopathy." (PMID 30515627, 2019).
tumor (3 papers, 2021 to 2022). "Additionally, PYROXD1 expression level was significantly increased in all the tumor stages S1-S4." (PMID 35845311, 2022). "While only the FOXM1, PYROXD1, hTERT and MCTP1 genes were overexpressed in CRC tumor tissues relative to the normal adjacent tissues at all the stages, but FOXM1, PYROXD1, hTERT, PIM3, BMI1, PPARA and MCTP1 were found to have stage-dependent expression." (PMID 35845311, 2022).
cancer (2 papers, 2022). A tumor composed of atypical neoplastic, often pleomorphic cells that invade other tissues. "The consistent expression of PYROXD1 across all the cancer stages may indicate that PYROXD1 gene contribute in many major biological pathways involved in cancer formation and progression." (PMID 35845311, 2022). "Previous literature confirmed the overexpression of PYROXD1 in several types of cancers." (PMID 36334145, 2022). "Despite accumulating evidence indicating that ROCK1 and PYROXD1 play vital roles in the metastasis of various cancers, the crosstalk between ROCK1 and PYROXD1 in LSCC is unknown." (PMID 36334145, 2022).
PYROXD1 also shares sentences with these, for which no sentence is quoted: axonal neuropathy (1 paper); breast carcinoma (1); cardiac diseases (1); centronuclear myopathy (1); connective tissue disorder (1); laryngeal squamous cell carcinoma (1); lung adenocarcinoma (1); neuromuscular genetic disease (1); neuropathy (1).